USP21 (ubiquitin specific peptidase 21)
Diseases named in the same sentence as USP21 in open-access papers (continued):
Sharing a sentence is not in itself a finding about the gene and the disease.
tumor (continued). "A series of in vitro experiments testified that USP21 regulated the expression of MAPK1 by binding to transcription factor GATA3, thereby regulating the tumor growth and cell stemness of GC." (PMID 33791299, 2021). "To investigate the effect of USP21 on tumor growth in vivo, we inoculated mice with NSCLC cells overexpressing USP21." (PMID 31956270, 2020). "USP21 promoted NSCLC cell proliferation, migration, and invasion and in vivo tumor growth by stabilizing a well-known oncogene, Yin Yang-1 (YY1), via mediating its deubiquitination." (PMID 31956270, 2020). "USP21 of USP sub family, prominently regulates several pathway signals to interact with MEK2 and deubiquitinate MEK2 directly, thus promoting the tumor growth in cells inducing stabilization of MEK2 by activating ERK1/2 pathway." (PMID 33192524, 2020). "Inhibition of USP21 in HCC cell lines decreased cell proliferation, anchorage-independent growth, cell cycle progression, and in vivo tumor growth." (PMID 29706623, 2018). "Due to the extended biological heterogeneity observed in HCC, it will, however, be important to determine to what extent USP21 and/or BRCA2 affect tumor growth across genetically distinct HCC subgroups." (PMID 28743957, 2017). "Together, these findings support the notion that USP21 promotes BRCA2 stability and protects from DNA damage accumulation in BRCA2-proficient tumor cells, which can in turn contribute to increased tumor growth and, ultimately, a more malignant phenotype." (PMID 28743957, 2017). "The identification of USP21 as a modulator of BRCA2 stability in HCC is, thus, expected to have important implications for both tumor growth and cancer therapy." (PMID 28743957, 2017). "Initially, it was observed that high USP21 resulted in a significant downregulation of immune regulators, including MHC molecules, immune stimulators, chemokines, and receptors, indicating a potential suppression of the tumor immune system." (PMID 38834869, 2024). "Importantly, EGF-treated USP21-KO HCT-15 cells developed significantly smaller tumor spheroids compared to EGF-treated Ctrl HCT-15 cells (E: USP21-KO HCT-15 treated with EGF vs. Ctrl HCT-15 treated with EGF)." (PMID 39695128, 2024). "USP21 is known to deubiquitinate and stabilize several transcription factors such as YY1, FOXM1, EZH2, Nanog, and GATA3, promoting cancer cell proliferation, migration, and invasion and in vivo tumor growth." (PMID 39305962, 2024). "Combining USP21 inhibition with immunotherapy, particularly ICB therapy, may enhance the anti-tumor effects." (PMID 38834869, 2024). "USP21 inhibitors are able to inhibit the deubiquitylation of MEK2 and FOXM1, which in turn down-regulates the expression of the ERK pathway and ultimately inhibits the growth of tumor cells." (PMID 39315102, 2024). "Additionally, disulfiram (DSF), an inhibitor against USP21 deubiquitylation activity, markedly abolished the USP21-mediated stability of G3BP1 protein and significantly displayed an anti-tumor effect on USP21-driving ESCC progression." (PMID 38906857, 2024). "USP21 deubiquitinated and stabilized MEK2, thus activating the ERK pathway for cell proliferation, colony formation, and cell cycle progression, and promoted tumor growth." (PMID 35884607, 2022). "Another DUB, USP21, was upregulated in PDAC cells and was found to promote tumor growth in vivo." (PMID 35884607, 2022). "Compared with the negative control group, the tumor weight and volume in the USP21 overexpression group were dramatically increased." (PMID 33791299, 2021). "USP21-mediated de-ubiquitination and stabilization of MAP2K2 promotes tumor growth of HCC." (PMID 34621787, 2021). "Furthermore, USP21 was found to interact directly with and deubiquitinate MEK2, and to promote the tumor growth of HCC cells by stabilizing MEK2 and activating ERK1/2 signaling." (PMID 29706623, 2018).
tumor (continued). "To gain mechanistic insight into USP21 function in HCC, we asked whether USP21 can modulate BRCA2 stability in HCC-derived tumor cells." (PMID 28743957, 2017). "In this study, we identify USP21 as a novel upstream regulator which interacts with and stabilizes FOXD1 and show that genetic or pharmacological inhibition of USP21 abrogates MES GSC-derived tumor growth in vitro and in vivo by antagonizing FOXD1 ubiquitination and degradation." (PMID 35974001, 2022). "However, how the deubiquitinases (CSN5, USP9X, USP21, OTUB1, and USP22) coordinatePD-L1 protein level in response to distinct tumor microenvironment signals remains unknown." (PMID 34741014, 2021). "Notably, BRCA2 overexpression failed to fully restore HCC tumor cell growth following USP21 depletion, suggesting that USP21 may have other targets in HCC." (PMID 35846989, 2022).
cancer (26 papers, 2016 to 2024). A tumor composed of atypical neoplastic, often pleomorphic cells that invade other tissues. "We identify six novel putative NESs inactivated in cancer, and we show that a cancer mutation predicted to disrupt the NES of USP21 leads to the aberrant nuclear accumulation of this protein." (PMID 27174732, 2016). "Moreover, cancer-related mutations in PD-L1, particularly at Asp276, enhance the USP21-mediated deubiquitination of PD-L1." (PMID 38474186, 2024). "The fact that USP21 is located in this amplified region may have obscured any association between USP21 expression with cancer survival." (PMID 28969054, 2017). "In addition, our search identified a cancer mutation that inactivates the NES of the human deubiquitinase USP21, and leads to the aberrant accumulation of this protein in the nucleus." (PMID 27174732, 2016). "Furthermore, USP21 has been shown to associate with both centrosomes and microtubules to regulate cell motility in three-dimensional matrices [29–, 33], and promotes cell proliferation and metastasis in kinds of cancer." (PMID 31253698, 2019). "The effect of USP21 deletion in cancer cells was studied in CRISPR/Cas9-edited USP21-targeting HAP-1 cells (HAP-1 USP21 KO) in comparison to HAP-1 parental control (HAP-1 WT)." (PMID 39305962, 2024). "This approach was an attempt to assess the role of USP21 in sensitization of cancer cells to chemotherapeutic agents." (PMID 39305962, 2024). "It has been reported that USP21 acts as a deubiquitinase to stabilize certain oncoproteins, which promotes the progression of many human cancers." (PMID 38906857, 2024). "Taken together, our findings indicate that targeting USP21 dysregulates the energy status of cancer cells offering new perspectives for anticancer therapy." (PMID 39305962, 2024). "Migration is another process that depends on ATP and an additional functional assay was used to evaluate the role of USP21 in cancer development." (PMID 39305962, 2024). "Disturbance of mitochondrial function, ATP synthesis, and STAT3 phosphorylation observed in HAP-1 cells with genetically inactivated USP21 suggested that the fundamental features of cancer cells, such as proliferation and adhesion are regulated by USP21." (PMID 39305962, 2024). "Among the USPs, USP21 is notable for interacting with multiple substrate proteins and is considered a critical oncogene in various human cancers." (PMID 39695128, 2024). "Due to its relevance in tumordevelopment and growth, USP21 has been reported as a promising noveltherapeutic target for cancer treatment." (PMID 36802665, 2023). "Our study provides novel insights into the regulatory mechanisms of YOD1 and USP21 in the context of the Hippo signaling pathway, and sheds lights on their potential as therapeutic targets for cancer treatment." (PMID 37743467, 2023). "Disulfiram, an anti-alcohol abuse drug actively being repurposed for cancer, and 6-Thioguanine (6 TG), a clinical drug for acute myeloid leukemia, were recently identified as competitive inhibitors of USP21." (PMID 35846989, 2022). "This encourages the evaluation of combination treatment with disulfiram and 6 TG for USP21 dysregulated diseases including cancer." (PMID 35846989, 2022). "Taken together, the present review aimed to provide fundamental insights into the potential of USP21 as a therapeutic target in diverse diseases, including cancer." (PMID 35846989, 2022). "Recent studies have shown that USP21 is frequently dysregulated in multiple types of cancer and plays a critical role in cancer development and progression." (PMID 35974001, 2022). "In basal-like breast cancer, USP21 can also regulate the cell cycle and paclitaxel sensitivity of cancer cells by deubiquitinating the transcription factor FOXM1." (PMID 33791299, 2021). "The IHC images of USP21 expression in CRC patient samples also illustrate the correlation between USP21 expression and cancer stage (right)." (PMID 31947604, 2020).
cancer (continued). "The oncogenic property of USP21 was confirmed by a significant reduction in liver metastasis when USP21-knockdown cancer cells were injected intrasplenically into mice." (PMID 31947604, 2020). "Consistently, the invasion activity of cancer cells was significantly induced by USP21, while USP21 knockdown reduced the Fra-1 effect." (PMID 31947604, 2020). "We found that USP21 significantly increased the migration activity of cancer cells, and USP21-knockdown reversely reduced cell migration." (PMID 31947604, 2020). "We provide evidence that USP21 limits anchorage-independent growth of transformed primary cells and cancer cell lines." (PMID 28969054, 2017). "Here the induction of FOXP3 degradation in Treg cells provides a potential method that enables transient inhibition of suppressive Treg cells, and thus USP21 is a potential drug target for future anti-cancer immunotherapy." (PMID 27857073, 2016). "In the present study, we investigate the effects of USP21 on proliferation, invasion and cancer stem cells (CSCs) property of RCC cell lines." (PMID 27259257, 2016). "Furthermore, we demonstrated that USP21 increased resistance of cancer cells to low dose of oligomycin." (PMID 39305962, 2024). "Disruption of cellular metabolism triggered by USP21 deletion proves that pharmaceutical inhibition of USP21 may decrease mitochondrial metabolism, leading to inhibition of cancer progression." (PMID 39305962, 2024). "In this study, we investigated the effect of USP21 deletion on cancer cell metabolism." (PMID 39305962, 2024). "Similarly, we observed that deletion of USP21 in HAP-1 cancer cells decreased ATP level, but the effect on oxygen consumption was the opposite." (PMID 39305962, 2024). "Interestingly, disulfiram (DSF), an inhibitor against the deubiquitylation activity of USP21, was demonstrated to possess obvious anti-cancer effects on the USP21-driving progression of ESCC." (PMID 38906857, 2024). "Ubiquitin Specific Peptidase 21 (USP21) is dysregulated in plenty of human cancers, however, its potential function and relevant molecular mechanisms in ESCC malignant progression as well as its value in clinical translation remain largely unknown." (PMID 38906857, 2024). "Moreover, emerging evidence suggests that Nanog has oncogenic features such as cancer stem cell maintenance, indicating a possible role of USP21/Nanog axis in carcinogenesis." (PMID 35846989, 2022). "USP21 is now known to deubiquitinate multiple well-known target proteins related to crucial processes involved in both cellular homeostasis and disease, especially cancer, where USP21 is frequently dysregulated." (PMID 35846989, 2022). "Collectively, these studies indicate that USP21 plays a critical role in the initiation and progression of various cancers, involving a set of key factors and regulatory networks, indicating that USP21 holds great promise as a potential target for the development of antitumor drugs." (PMID 35846989, 2022). "Accumulating evidence has shown that USP21 exert oncogenic functions in a variety of human cancers." (PMID 35974001, 2022). "In summary, highly potent and specific inhibitors targeting USP21 urgently need to be discovered and developed, which may serve as promising agents for the treatment of multiple forms of cancer and other diseases." (PMID 35846989, 2022). "Since we demonstrated that USP21 enhances AP-1 target gene expression, combinatorial treatment of immune checkpoint blockers with USP21 knockdown could be beneficial for cancer immunotherapy." (PMID 31947604, 2020). "Next, we sought to investigate the expression of USP21 protein in human cancer." (PMID 28969054, 2017). "However, we noted that USP21 is located in region 1q21 of chromosome 1, which is frequently amplified in human cancers." (PMID 28969054, 2017).
cancer (continued). "These apparently opposite effects of USP21 in different cancers and cell lines suggest that the impact of USP21 depletion may depend on the underlying pattern of genetic and epigenetic alterations found in different tumors and cellular contexts." (PMID 28969054, 2017). "Thus, we provide evidence presenting USP21 as an attractive therapeutic target for cancer." (PMID 39305962, 2024). "Previous investigations testified that USP21 could participate in the progression of cancer." (PMID 33791299, 2021). "However, whether USP21/YY1/SNHG16 plays a cancer-promoting role in a feedback loop needs to be further studied." (PMID 31956270, 2020). "Indeed, we observed that the intensity of USP21 protein down-regulation became less profound in more advanced cancers, suggesting that selection for regional amplification might lead to a secondary increase in USP21 concomitant with disease progression." (PMID 28969054, 2017). "Conversely, in tumors with downregulated USP21, EGFR undergoes ubiquitination and subsequent degradation within MVB-lysosome vesicles, leading to reduced cancer progression due to diminished EGF engagement." (PMID 39695128, 2024). "Further explanation of the mechanism of USP21-dependent STAT3 translocation to mitochondria, leading to mitochondrial protein translation, can significantly expand our understanding of cancer metabolism." (PMID 39305962, 2024). "Another issue that needs to be clarified is that although USP21 protein levels could distinguish ESCC tumors from their matched normal tissues, its diagnostic value for ESCC should be validated using the standard approach which would require matched biopsies from non-cancer patients." (PMID 38906857, 2024). "Our immunoprecipitation experiment indicates that USP21 directly interacts with STAT3 and positively regulates STAT3 expression level in cancer cells." (PMID 39305962, 2024). "Enhanced tyrosine phosphorylation of STAT3 in the presence of USP21 in HAP-1 and A549 cells suggests that USP21-dependent regulation of STAT3 signaling pathway is common for various cancer cells." (PMID 39305962, 2024). "Most importantly, we validated the oncogenic property of USP21 in human CRCs by demonstrating that USP21 was highly upregulated in CRC patient samples, especially in high-grade cancers." (PMID 31947604, 2020). "Among the tested DUBs, we newly identified USP21 to play an oncogenic role in CRC as a Fra-1 DUB and to regulate a Fra-1 target gene involved in cancer metastasis." (PMID 31947604, 2020). "Additionally, we have found that the deletion of USP21 reduced STAT3 activation and STAT3-dependent gene and protein expression in cancer cells." (PMID 39305962, 2024). "Taken together, normalized results indicate that lack of USP21 increases sensitivity of cancer cells to both nonspecific anticancer drug such as DOX and specific mitochondrial inhibitors, resulting in distortion of cellular bioenergetics and cell viability." (PMID 39305962, 2024). "Our findings present USP21 DUB as a positive controller of STAT3 activity and cancer metabolism." (PMID 39305962, 2024). "Like USP2, USP21 was also reported to deubiquitinate RIP1 and the selective USP21 inhibitor compound BAY-805 may have therapeutic potential in cancer." (PMID 37892185, 2023). "Several E3 ligase (Cullin3-SPOP, c‐Cbl, and β-TrCP) and deubiquitinases (CSN5, USP9X, USP21, OTUB1, and USP22) have been reported to regulate PD-L1 protein degradation in cancer cells, indicating posttranslational modification plays an important roles in regulation of PD-L1 stability." (PMID 34741014, 2021). "We did not observe a significant correlation between USP21 protein expression and overall cancer survival, for the 89 paired samples with patient survival information." (PMID 28969054, 2017). "We asked whether USP21 regulates the stability of Gli1 and turned to CRISPR-CAS9 technology to knockout USP21 in HEK293T cells, which, like many cancer cells, show autonomous expression of Gli1." (PMID 27621083, 2016).
cancer (continued). "Additionally, we show that lack of USP21 regulates mitochondrial respiration determining metabolism of cancer cells to proliferate and migrate." (PMID 39305962, 2024).
infection (3 papers, 2015 to 2021). The state of being infected such as from the introduction of a foreign agent such as serum, vaccine, antigenic substance or organism. "Considering that protection from S. japonicum infection mainly depends on the clearance of S. japonicum in the early stage of infection, USP21−/− Tregs might inhibit the ability of mice to cause the death of S. japonicum." (PMID 33628844, 2021). "We measured the levels of IFN-gamma, IL-4, IL-10, IL-17A, IL-23, and IL-9 in the serum samples and PBMCs from the KO and WT mice at different stages of infection to conduct and extensive analysis of how USP21-deficient Tregs affect the resistance of mice to S. japonicum." (PMID 33628844, 2021). "We derived Usp21Loxp/Loxp ESCs by intercrossing Usp21Loxp/Loxp mice; Usp21 was knocked out by infection with a lentivirus carrying Cre recombinase." (PMID 27886188, 2016). "This suggests that loss of USP21 did not have significant impact on the immune resistance to bacterial challenge at least in this mouse infection model." (PMID 25680095, 2015).
immune disorders (2 papers, 2016 to 2021). "Mice depleted of Usp21 specifically in Treg cells display immune disorders characterized by spontaneous T-cell activation and excessive T-helper type 1 (Th1) skewing of Treg cells into Th1-like Treg cells." (PMID 27857073, 2016). "We find that mice lacking USP21 in Treg cells suffer from immune disorders characterized by spontaneous T-cell activation and excessive T-helper type 1 (Th1) skewing." (PMID 27857073, 2016). "Therefore, we speculated that the absence of USP21 might inhibit the Th17-type immune response, which exerted a positive effect on the reduction of liver immunopathological damage and might also lead to immune dysfunction in the host." (PMID 33628844, 2021).
bacterial infections (1 paper, 2015). "Our work complements the findings of Fan et.al., addressing the role of USP21 in hematopoiesis, lymphocyte development, and immune response to bacterial infections." (PMID 25680095, 2015). "The possible roles of USP21 in immune responses to bacterial infection currently remain untested." (PMID 25680095, 2015).
USP21 also shares sentences with these, for which no sentence is quoted: adenocarcinoma (1 paper); Autoimmunity (1); bladder tumors (1); colorectal adenocarcinoma (1); esophageal squamous cell carcinoma (1); lung adenocarcinoma (1); metabolic disease (1); metastatic colorectal cancer (1); nasopharyngeal carcinoma (1); pulmonary fibrosis (1); stomach cancers (1); teratoma (1).